LIG1 (DNA ligase 1)
Diseases named in the same sentence as LIG1 in open-access papers (continued):
Sharing a sentence is not in itself a finding about the gene and the disease.
tumor (29 papers, 2004 to 2025). "Moreover, real-time RT–PCR analysis showed a loss of Lig-1 expression in tumour cell lines relative to normal tissues, raising the possibility that Lig-1 is the product of a tumour-suppressor gene." (PMID 14735165, 2004). "Positioned at 19q13.2-13.3, LIG1, one of the four DNA ligases in mammalian cells, is frequently deleted in tumour cells of diverse origins." (PMID 39234248, 2024). "There is also a noticeable difference in the expression of LIG1 in epithelial cells between the healthy and tumour groups." (PMID 39234248, 2024). "LIG1 is one of the four DNA ligases in mammalian cells, and its gene is located at 19q13.2-13.3, a region often deleted in various types of tumour cells." (PMID 39234248, 2024). "22Rv1 control (sgNTC) and LIG1-KO (sgLIG1 and sgLIG1) cells were injected into both flanks of each mouse and tumor growth was monitored." (PMID 39718835, 2024). "The clinical relevance of the SL interaction between LIG1 and PARP, was confirmed by testing the combination of LIG1 loss and PARP inhibition across diverse preclinical tumor models, including a PCa xenograft mouse model." (PMID 39718835, 2024). "At present, the literature shows that LIG1 is a DNA ligase that is usually overexpressed in tumours." (PMID 35379200, 2022). "207/442 (46.8%) tumours were low for LIG1 expression and 234 (53.2%) of the tumours were high in expression." (PMID 34373746, 2021). "Patients whose tumours had high LIG1/high XRCC1 had worse PFS after platinum-based chemotherapy compared to patients whose tumours had low LIG1/low XRCC1 co-expression." (PMID 34373746, 2021). "Tumours with high LIG1 nuclear expression were likely to be platinum resistance although this was non-significant (p = 0.063)." (PMID 34373746, 2021). "Targeted deletion of LIG1 in mouse embryos was found to be lethal and antisense oligonucleotides targeting LIG1 transcripts in human tumours have achieved effective suppression of tumour growth." (PMID 30590694, 2019). "Consistently, LigI is up regulated in tumor cell lines while a strong reduction of LIG1 gene expression is triggered by cell confluence, serum starvation and cell differentiation." (PMID 26151554, 2015). "Together, these properties suggest a dependence on DNA ligase 1 in tumor cells during oncogene induced replicative stress." (PMID 20454618, 2010). "Specifically, lig1 and the arp2 related gene were deleted in PyV MT/jnk2−/− tumor in comparison to jnk2−/− mammary gland and PyV MT/jnk2+/+ tumors." (PMID 20454618, 2010). "In addition, variants in MMR pathway genes, MSH3, MSH6, LIG1, MCM9, and POLD3, were associated with relatively high MSI score and/or high mutational burden in 6 tumor samples." (PMID 41353477, 2025). "This synthetic lethality (SL) is conserved across multiple tumor types (e.g., lung, breast, and colorectal), and its applicability might be extended to LIG1-functional tumors through a pharmacological combinatorial approach." (PMID 39718835, 2024). "Upon exploring expression levels, we observed that LIG1 expression was significantly elevated in epithelial cells and endothelial cells, leading us to hypothesise that LIG1 may play a role in tumour proliferation." (PMID 39234248, 2024). "A total of 442 tumours were suitable for analysis of LIG1 nuclear expression." (PMID 34373746, 2021). "Similarly, OS was poor in patients whose tumours had high LIG1/high XRCC1 compared to patients whose tumours had low LIG1/low XRCC1 co-expression." (PMID 34373746, 2021). "However, the impact of Lig-1 on ErbB receptor signalling and on the regulation of tumour cell growth remains to be determined." (PMID 14735165, 2004).
tumor (continued). "Additionally, KEGG analysis suggested that LIG1 might affect tumour proliferation and invasiveness through the EMT pathway." (PMID 39234248, 2024). "As well as in EESCC, cell cycle (e.g., PCM1, LIG1, etc.)and glycolysis (e.g., PGK2, ENO3, etc.)were predominant in the tumor tissues of EDAC." (PMID 35397555, 2022). "Other key repair genes such as FEN-1, LIG1, XPA and TOP3A were also found downregulated indicating reduced tumor progression, chemo-resistance, alternative end-joining (Alt-EJ) and nucleotide excision repair (NER)." (PMID 34680264, 2021). "We observed that LIG1, MRE11A, RAD9 and SMC1A levels were up-regulated in tumor cell lines when compared to normal PHK or to PHK expressing HPV genes." (PMID 30674977, 2019). "PCNA and FEN1 expression were significantly above tumor average in subtype 2, as were EXO1 and LIG1." (PMID 31857847, 2019). "We searched for LIG1-specific inhibitors and tested whether LIG1 and PARP combined pharmacological inhibition is effective in PCa and other tumor models." (PMID 39718835, 2024). "Our results suggest that LIG1-specific inhibitors could expand the opportunities for PCa and BRCA patient treatment, whereas other tumor types, such as LUAD and COAD, seem to be less responsive to the combined pharmacological inhibition of LIG1 and PARP." (PMID 39718835, 2024). "The SL between LIG1 and PARP has therapeutic potential in multiple tumor models." (PMID 39718835, 2024). "Collectively, these findings indicate that the LIG1 and PARP SL interaction could be exploited for the treatment of multiple tumor types, beyond PCa." (PMID 39718835, 2024). "Patients whose tumours had high LIG1 nuclear expression had significantly poorer progression free survival (PFS) (p = 0.001) and overall survival (OS) (p = 0.037) compared patients with low LIG1 nuclear expressing tumours." (PMID 34373746, 2021). "Furthermore, Lig3, Lig1 and PARP1 silencing also significantly blocked protein expression of neuronal developmental and NBL tumor markers (TH, Phox2b, TRKB) in differentiating NCSC-MYCN cells, quantified by Western blot analysis." (PMID 29238067, 2017). "An important question is whether Lig3, Lig1, or PARP1 inhibition could block tumor development, an area of our ongoing studies." (PMID 29238067, 2017). "Additionally, we found support for the SL interaction between LIG1 and PARP1 and EME1 and PARP1 by analyzing the coexpression of LIG1, EME1, or FAAP24 and PARP1 in relation to the tumor, node, metastasis (TNM) stage of PCa samples (P value for LIG1-PARP1 < 0.001; P value for EME1-PARP1 < 0.05)." (PMID 39718835, 2024). "In the four HR gene mutation cases, three of them (PDX1, PDX2, PDX3) exhibited statistically significant decrease in tumor burden when treated with Olaparib (P < 0.05 for all cases) and unsurprisingly all harbored BRCA1/2 mutation while the PDX4 who carried LIG1 mutation did not respond to Olaparib." (PMID 32005272, 2020). "Therefore, downregulation of these DDR genes e.g., RAD51C, LIG1 and POLD1-3 may produce synergies towards formation of persistent unrepairable complex DSB in tumor cells treated with dual combination leading to cell growth arrest and lethality." (PMID 30042828, 2018). "Collectively, these results provide new evidence that these three factors (Lig3, Lig1, and PARP1) have a functional role in MYCN oncogenic activity in human NCSC, and sets precedence to investigate alt-NHEJ and non-canonical DNA repair factors in NBL tumor initiation and progression." (PMID 29238067, 2017).
infection (4 papers, 2012 to 2025). The state of being infected such as from the introduction of a foreign agent such as serum, vaccine, antigenic substance or organism. "The protein levels of NTHL1, MUTYH, FEN1, RAD51, POLD1, and LIG1 were observed to be decreased, during the infection, in a CagA- and phospho-CagA-related manner in both cell lines." (PMID 33339161, 2020). "Our study showed that infection can promote an imbalance between APE1 and the downstream proteins of LP-BER FEN1, POLD1, and LIG1." (PMID 33339161, 2020). "Our data suggest that the accessory components (RFC2, RFC3, RFC5, PCNA), polymerases (POLD1, POLD2, POLD3, POLE, POLE2, POLE4), and ligase LIG1, were downregulated during infection, for which the downregulation of RFC5, POLD1, POLD2, POLD3, POLE, and LIG1 was CagA-related." (PMID 33339161, 2020). "Upon infection, the levels of HBV cccDNA and core protein were markedly lower in HepG2-NTCP cells with LIG1 or LIG3 knock-down compared to the control knock-down cells, suggesting that LIG1 and LIG3 are also required for the first round HBV cccDNA formation during de novo infection." (PMID 29287110, 2017).
LIG1 also shares sentences with these, for which no sentence is quoted: breast carcinoma (6 papers); colorectal cancer (3); Fanconi anemia (3); inborn error of immunity (2); LIG4 syndrome (2); lung adenocarcinoma (2); lymphoma (2); Nijmegen breakage syndrome (2); Anaemia (1); Ataxia (1); ataxia telangiectasia (1); autoimmune disease (1); Autoimmunity (1); B-cell lymphoma (1); breast (1); combined immunodeficiency (1); developmental delays (1); esophageal squamous cell carcinoma (1); Fanconi anemia complementation group A (1); head & neck cancers (1); hepatocellular carcinoma (1); HIV-1 infection (1); Hyperglycemia (1); leukopenia (1); low grade glioma (1); macrocytic anemia (1); magnesium deficiency (1); myotonic dystrophy type 1 (1); Neurofibrillary tangles (1); neutropenia (1).
A further 5 diseases each share a sentence with LIG1 in 1 paper.